LEP (leptin)
Diseases named in the same sentence as LEP in open-access papers (continued):
Sharing a sentence is not in itself a finding about the gene and the disease.
Insulin resistance (continued). "Elevated serum leptin, particularly in obese individuals, is a warning sign of energy imbalance, hyperinsulinemia, insulin resistance and other metabolic risk factors that are strongly associated with type 2 diabetes." (PMID 25306890, 2015). "A possible underlying mechanism has been reported by previous studies that showed parental diabetes is associated with higher levels of insulin resistance, serum glucose, C-peptide, and leptin levels." (PMID 26322779, 2015). "Hypothalamic SIRT1 can improve these disruptions by acting on several targets that cause central leptin/insulin resistance." (PMID 26236282, 2015). "Activation of proopiomelanocortin neurons by leptin has been shown to enhance insulin secretion and degree of insulin resistance and β-cell function are associated with leptin in patients with Type 2 diabetes." (PMID 25723719, 2015). "Higher leptin and lower adiponectin levels were shown to be associated with obesity, dyslipidemia, insulin resistance, hypertension and inflammatory states, conditions which are involved in the pathogenesis of CKD." (PMID 25793395, 2015). "Other multiple pathogenic links that have been reported are insulin resistance, hyperglycemia, leptin hormonal dysfunction, autonomic neuropathy, and oxidative stress." (PMID 25705222, 2015). "Leptin and insulin resistance are both associated with aging and much evidence exists to show the amelioration of these metabolic disorders by CR." (PMID 26061745, 2015). "The associated metabolic abnormalities include: insulin resistance, diabetes, dyslipidaemia and low leptin levels." (PMID 25885670, 2015). "Prospective studies have shown that GDM is linked to the down-regulation of adiponectin and anti-inflammatory cytokines (e.g., IL-4 and IL-10) and up-regulation of leptin and pro-inflammatory cytokines implicated in insulin resistance (e.g., IL-6 and TNF-α)." (PMID 26110385, 2015). "LV wall thickness has been positively correlated with insulin resistance in hypertension, and leptin has been associated with insulin resistance." (PMID 26064110, 2015). "In view of these findings, leptin and adiponectin are likely to be more important in the pathogenesis of pregnancy-associated insulin resistance as compared to resistin." (PMID 25202741, 2014). "One study showed that loss of functional Sfrp5 mitigated increases in serum leptin levels, as well as the induction of glucose intolerance and insulin resistance after high-fat feeding." (PMID 24465779, 2014). "High cord blood leptin levels have been positively correlated with birth weight and insulin resistance, whereas low cord blood leptin levels have been associated with small for gestational age." (PMID 25336252, 2014). "We employed a serial multiple-mediator model with leptin and insulin resistance values as serial mediators of the association between activity in the VS and individual BMI levels." (PMID 25368558, 2014). "Elevated circulating leptin concentration has been associated with obese patients with insulin resistance compared to normal weight individuals." (PMID 24690978, 2014). "Leptin is associated with general and abdominal obesity, dyslipidemia, and insulin resistance in Kyrgyz patients." (PMID 24981337, 2014). "Other data demonstrate that mild maternal Zn deficiencies are associated with elevated leptin concentrations and insulin resistance in male offspring in adulthood." (PMID 23708056, 2014). "Of late, the serum/plasma leptin: adiponectin ratio (L : A) has been reported to be associated with dyslipidemia and insulin resistance." (PMID 24741591, 2014). "We studied associations of height, body composition (by dual-energy X-ray absorptiometry) and cardiovascular risk markers (insulin resistance (IR), leptin) in children." (PMID 24509503, 2014). "Leptin has also been associated with type-2 diabetes mellitus and the insulin resistance characteristic of this disease." (PMID 24825928, 2014).
Insulin resistance (continued). "Obese and insulin-resistant patients exhibit higher leptin plasma levels than control subjects, i.e. they become leptin-resistant, exhibiting a loss of leptin effects." (PMID 25352918, 2014). "To probe the role of MK in vivo, we then examined its expression levels in epididymal adipose tissue of ob/ob mice, a well-characterized model of severe genetic obesity and insulin resistance due to leptin deficiency." (PMID 24516630, 2014). "Visceral fat is metabolically active and is an important site for adipokines such as adiponectin and leptin, that can modulate inflammation and insulin resistance, and impart cardiovascular risk." (PMID 25005601, 2014). "Among these proinflammatory cytokines, TNF-α and leptin have been suggested as the strongest predictors of pregnancy-associated insulin resistance." (PMID 25202741, 2014). "Both adiponectin and leptin have been implicated in the causation of dyslipidemia and insulin resistance." (PMID 23533722, 2013). "For example, leptin, a proinflammatory agent, directly associated with the amount of adipose tissue, is related to insulin resistance and progression of colon cancer in experimental studies." (PMID 23819063, 2013). "Leptin also plays a critical role in the inflammatory response and has been associated with insulin resistance and metabolic syndrome." (PMID 24455217, 2013). "The leptin deficient mouse (ob/ob) develops massive fatty liver as well as obesity and insulin resistance." (PMID 23554788, 2013). "Masuyama and Hiramatsu found that mice offspring exposed to high fat diet during pregnancy developed insulin resistance and hyperlipidemia at 24 wks of age, which was associated with altered levels of leptin in adipose tissue." (PMID 24455747, 2013). "Levels of fasting blood glucose (FBG), insulin, leptin, and leptin receptors were measured by enzyme linked immunosorbent assay (ELISA), and homeostasis model assessment of insulin resistance (HOMA-IR) was calculated." (PMID 24102053, 2013). "Low adiponectin and high leptin levels can cause insulin resistance in adipocytes thus leading to diabetes." (PMID 23840254, 2013). "The OR group showed weight loss and normalized levels of adiposity, insulin resistance, serum leptin and genotoxicity, thus having features similar to those of the C group." (PMID 23468891, 2013). "We observed that consumption of the dietary supplement was associated with a significantly greater decrease in insulin resistance, assessed by homostasis model assessment (p < 0.001), leptin/adiponectin ratio (p < 0.04), respiratory quotient (p < 0.008)." (PMID 23271695, 2013). "Leptin deficient mice that have a mutation in the leptin gene are overweight, develop severe insulin resistance, and serve as a model for type 2 diabetes and the metabolic syndrome." (PMID 23936084, 2013). "Adiponectin and the ratio of adiponectin to leptin were also employed to create dichotomous groups of insulin resistance and dyslipidemia risk factors." (PMID 23533722, 2013). "Activation of NF-κB is a common characteristic of many tumors and is associated with insulin resistance and elevated circulating levels of leptin, insulin, or IGF-1." (PMID 24280167, 2013). "An elevated circulating leptin level is a marker of leptin resistance and is independently associated with insulin resistance, and is commonly observed in the obese." (PMID 24244369, 2013). "Low levels of adiponectin, high levels of leptin and chronic low-grade inflammatory state are generally observed in the obese status and have been associated with insulin resistance and metabolic syndrome." (PMID 23433085, 2013). "In Caucasian patients with type 2 diabetes who were also overweight and middle-aged, leptin levels were significantly associated with insulin secretion and insulin resistance, and with insulin secretion in patients undergoing oral drug therapy." (PMID 23853613, 2013).
Insulin resistance (continued). "Disruption of adiponectin causes a phenotype of insulin resistance in mice and over-expression of adiponectin improves insulin sensitivity wild-type and leptin deficient obese mice." (PMID 23826141, 2013). "To eliminate concerns related to potential impact of leptin signaling deficiency in db/db or ob/ob mice, we examined the effects of Tff3 activation on glucose intolerance and insulin resistance in diet-induced obese (DIO) mice." (PMID 24086476, 2013). "Adipocytokines such as TNF-α, adiponectin, resistin, and leptin, synthesized and secreted by adipocytes, have been found to be linked to insulin resistance associated with obesity." (PMID 24294136, 2013). "In humans, insulin resistance is associated with elevated plasma leptin levels independently of body fat mass." (PMID 24455420, 2013). "Leptin directly inhibits insulin secretion from pancreatic β-cells and elevated serum leptin levels are associated with fasting insulin, insulin resistance (HOMA-IR), and total cholesterol, the core metabolic disturbances of the metabolic syndrome." (PMID 24455217, 2013). "Despite a sometimes severe weight loss at late stages of the disease, HD patients have been described to display increased appetite, insulin resistance, alteration in leptin levels and higher susceptibility to develop diabetes." (PMID 24376631, 2013). "The ob/ob mouse strain, from the Bar Harbor-Jackson laboratory, has a well-known feature of leptin deficiency because of the mutation identified in leptin gene leading to severe insulin resistance." (PMID 23671868, 2013). "Considerable data suggest that chronic sleep loss can result in insulin resistance and changes in appetite-regulating hormones, such as increased ghrelin and decreased leptin." (PMID 23360346, 2013). "In middle-aged adults leptin was a predictor of the metabolic syndrome, insulin resistance, and hyperinsulinemia and positively associated with metabolic syndrome independent of measures of body fat." (PMID 24455217, 2013). "Higher leptin levels were also associated with insulin resistance in RA, although they paradoxically attenuated the effect of insulin resistance on severity of coronary calcification." (PMID 24376307, 2013). "This study demonstrates that chronic central leptin administration causes a serum inflammatory profile correlated to insulin resistance." (PMID 23056516, 2012). "Chronic IH has been shown to cause insulin resistance and glucose intolerance in obese leptin-deficient mice as well as inducing hyperlipidemia in lean mice." (PMID 22870336, 2012). "The visceral fat component is metabolically active and it regulates numerous adipocytokines such as leptin and adiponectin, which have been associated with insulin resistance." (PMID 22301198, 2012). "Higher waist circumference and the BMI are associated with higher insulin resistance and leptin production, and both reduce uric acid excretion." (PMID 22475652, 2012). "In ad libitum fed animals, serum leptin, insulin, and glucose were significantly increased in mice deficient in SP-D, and indicative of insulin resistance." (PMID 22509382, 2012). "Higher waist circumference and BMI are associated with higher insulin resistance and leptin production, and both reduce renal uric acid excretion, thus increasing its concentration." (PMID 22475652, 2012). "In the present study, we analyzed the subcutaneous, visceral, and total fat ratio in three groups of mice because visceral and subcutaneous fat is associated with metabolic syndrome (leptin and adiponectin secretion, and insulin resistance) in humans." (PMID 22587351, 2012). "Increased circulating leptin, a marker for leptin resistance, is thought to be associated with insulin resistance and metabolic syndrome." (PMID 22748134, 2012). "Inflammation has been implicated in the hypothalamic leptin and insulin resistance resulting defective food intake during high fat diet period." (PMID 22844271, 2012).
Insulin resistance (continued). "In prepubertal children, leptin emerges as a sex-independent discrimination marker of adiposity degree and as a useful, sex-associated predictor of the systemic insulin resistance." (PMID 21365005, 2011). "The overall aims of this study were therefore to investigate sex differences and associations of HMW adiponectin, leptin and proinflammatory adipokines with adiposity and insulin resistance measures in prepubertal age." (PMID 21365005, 2011). "Whereas there are contrasting data about the association of leptin/adiponectin ratio and vascular damage, it is largely accepted that this ratio is strongly associated with insulin resistance, which represents the major feature of the MS." (PMID 22114592, 2011). "While leptin and insulin resistance are clearly associated with NAFLD, there is some indirect evidence supporting a primary role of increased delivery of non-esterified fatty acids to liver as a cause of hepatic steatosis in murine models." (PMID 22125617, 2011). "Previously, some relate demonstrated hepatic insulin resistance associated with a high fructose intake, independent of changes in body composition, and serum free fat acid and leptin concentration." (PMID 20979642, 2010). "The high-KAA diet was fed to leptin-deficient ob/ob mice that had already developed noticeable insulin resistance and hepatic steatosis before KAA treatment." (PMID 20706589, 2010). "Increased TNFα, leptin, and resistin levels and decreased adiponectin expression in adipose tissues are associated with the development of insulin resistance and vice versa." (PMID 20148112, 2010). "BPA exposure aggravated the insulin resistance produced during pregnancy and was associated with decreased glucose tolerance and increased plasma insulin, triglyceride, and leptin concentrations relative to controls." (PMID 20488778, 2010). "The expression of TNF-α, IL-6, MCP-1, and leptin is upregulated in the adipose tissue of obese mice which is closely associated with insulin resistance." (PMID 21403905, 2010). "Leptin, IL-6, and inflammatory mediators have also been implicated in the pathogenesis of insulin resistance and other features of metabolic syndrome." (PMID 20224753, 2010). "In summary, low circulating concentrations of leptin, increased fat oxidation and insulin resistance are associated with increased circulating concentrations of cortisol and interleukin-6 in weight-losing patients with pancreatic cancer." (PMID 15026790, 2004). "Taken together, the results of the present small study would suggest that weight loss in pancreatic cancer patients is associated with an increase in catabolic mediators, insulin resistance and a reduction in leptin concentrations." (PMID 15026790, 2004). "Nevertheless, this finding suggests that leptin may not have a direct causal role in insulin resistance but rather that both leptin and insulin resistance may result from common pathways linked to increasing adiposity." (PMID 40630340, 2025). "In contrast, another cohort study demonstrated that high serum leptin was associated with an increased risk of frailty—including weakness and exhaustion—even after adjusting for fat mass, insulin resistance, and inflammation, suggesting broader systemic effects beyond adiposity." (PMID 40647619, 2025). "In addition to leptin, adipokines such as resistin, which is linked to inflammation and insulin resistance, also likely to decrease with improvements in adiposity and insulin sensitivity." (PMID 41309556, 2025). "Personalized Psychiatry and Genomic Risk Profiling: Emerging research suggests that genetic polymorphisms affecting dopamine, serotonin, and leptin pathways may predict susceptibility to antipsychotic-induced weight gain and insulin resistance." (PMID 41487746, 2025). "Additionally, increased cytokine production associated with leptin and insulin resistance heightens the risk of autoimmune thyroid diseases." (PMID 39857741, 2025).
Insulin resistance (continued). "Resistin is another adipokine implicated in the pathophysiology of insulin resistance and is found at elevated levels in individuals with a higher BMI, showing strong positive correlations with leptin and insulin concentrations, thereby reinforcing its involvement in glucose dysregulation." (PMID 41334336, 2025). "Specifically, cardiorespiratory fitness can modulate leptin’s signaling pathway in skeletal muscles, while higher levels of leptin are associated with higher levels of insulin and, consequently, with insulin resistance, due to a break in the insulin signaling pathway caused by hyperinsulinemia." (PMID 39860463, 2025). "Similarly, studies on saccharin consumption in Wistar rats revealed weight gain without an increase in total caloric intake or associations with insulin resistance, fasting leptin, or peptide YY (PYY) levels." (PMID 40873447, 2025). "Lower insulin resistance has been associated with improved leptin sensitivity in previous studies." (PMID 40087612, 2025). "Reduced leptin production is associated with a lower basal metabolic rate, which makes weight loss more difficult and increases the risk of conditions such as type 2 diabetes and insulin Resistance." (PMID 40622971, 2025). "This likely explains why high leptin was associated with greater insulin resistance in this study." (PMID 40214973, 2025). "In addition to leptin and adiponectin, it is linked to insulin resistance, inflammation, and adipogenesis." (PMID 41010935, 2025). "Higher leptin levels are associated with insulin resistance." (PMID 39018497, 2025). "Leptin was associated with an increase in insulin resistance as its levels increased." (PMID 40214973, 2025). "However, human studies indicate that variability in tissue leptin sensitivity contributes to inconsistent associations between circulating leptin and insulin resistance across individuals." (PMID 41002965, 2025). "Elevated leptin levels are associated with insulin resistance and type 2 diabetes mellitus (T2DM)." (PMID 38397015, 2024). "While leptin and adiponectin as individual biomarkers in our current review do not show consistent associations, new research indicates that the ratio of leptin to adiponectin (L/A) has greater accuracy as a biomarker for insulin resistance in adolescents." (PMID 39519417, 2024). "Notably, another study reported an association between serum leptin levels and hyper-fasting serum insulin levels, demonstrating the correlation between leptin levels and insulin resistance in PCOS patients." (PMID 39459443, 2024). "Furthermore, it is associated with hormonal and metabolic disorders, in which adipose tissue-derived hormones, adiponectin and leptin, play an important role in energy homeostasis and insulin resistance-associated metabolic syndrome." (PMID 39727798, 2024). "Furthermore, inhibition of iNOS or NF-kB decreases insulin resistance in leptin-deficient obese mouse models." (PMID 38347961, 2024). "A lower expression of anti-inflammatory adipokines (eg, adiponectin) and higher expression of proinflammatory adipokines (eg, leptin, resistin, visfatin) contributes to the systemic subclinical inflammation and progressive insulin resistance with increased risk of type 2 diabetes." (PMID 37934800, 2024). "Additionally, ROS can trigger inflammation, causing the release of TNF-α, leptin, and GH, and this cascade ultimately results in insulin resistance, accelerated muscle breakdown, and the loss of muscle mass." (PMID 39286235, 2024). "Indeed, while intra-abdominal fat accumulation correlates with insulin resistance, subcutaneous adipose tissue deposition is more strongly associated with circulating leptin levels." (PMID 39409194, 2024). "An increased leptin level is associated with insulin resistance and T2DM development." (PMID 36901837, 2023).